DSCR10 (Down syndrome critical region 10)
Gene: Long non-coding RNA gene on chromosome 21 (38,206,156 to 38,208,644, forward strand). Ensembl gene ENSG00000233316.
Diseases named in the same sentence as DSCR10 in open-access papers:
DSCR10 is named in the same sentence as 1 disease in open-access papers, as found by Europe PMC text mining. Sharing a sentence is not in itself a finding about the gene and the disease. The quoted sentences say what the papers report.
cancer (1 paper, 2020). A tumor composed of atypical neoplastic, often pleomorphic cells that invade other tissues. "Relevant studies on the function of DISC1-IT1, SYNPR-AS1 DSCR10, STEAP2-AS1, and hsa-mir-31 in cancer do not exist in the literature." (PMID 33042838, 2020).